GDF15 (growth differentiation factor 15)
Diseases named in the same sentence as GDF15 in open-access papers (continued):
Sharing a sentence is not in itself a finding about the gene and the disease.
heart failure (continued). "This relevance was strikingly shown, where inhibition of GDF15 activity had a substantial impact on the development of severe heart failure and the necessity for euthanasia." (PMID 39312445, 2024). "The secondary end point of death or heart failure was associated with RDW (HR: 1.40; 95% CI: 1.19-1.67), NT-proBNP (HR: 2.97; 95% CI: 2.16-4.06), hs-troponinT (HR: 1.35; 95% CI: 1.09-1.67), and GDF-15 (HR: 1.80; 95% CI: 1.28-2.56)." (PMID 39157753, 2024). "GDF-15 has a low biological fluctuation range, is stable during acute events, and has been investigated as a prognostic marker in patients with heart failure." (PMID 39768671, 2024). "Increased levels of GDF-15 were noted in cardiomyocytes during ischemia–reperfusion injury and myocardial infarction, which led to the notion that GDF-15 can be used as a marker of cardiac failure." (PMID 37444400, 2023). "Novel biomarkers such as PENK, ST-2, GDF-15, Pentraxin-3, Galectin-3, and Osteopontin have recently emerged as potential prognostic indicators in heart failure patients." (PMID 36902318, 2023). "Given its properties, GDF-15 has been tested as a prognostic marker in multiple diseases, including coronary heart disease, heart failure, atrial fibrillation, and cancer." (PMID 37008733, 2023). "Increasedplasma levels of GDF-15 can be detected in patients suffering from myocardialinfarction, or as a result of injury and heart failure." (PMID 39077481, 2023). "The circulating level of GDF-15 increases rapidly in response to cardiovascular injury, such as pressure overload, heart failure, ischemia/reperfusion, and atherosclerosis." (PMID 37888100, 2023). "Blood GDF-15 concentrations have been observed to spike quickly after cardiovascular injury due to heart failure, ischemiareperfusion and atherosclerosis." (PMID 36864452, 2023). "In plasma proteome analysis of patients with heart failure, diabetic patients had higher circulating GDF-15 and galectin-4 levels, and over-representation of pathways related to inflammation, cardiac remodeling, and fibrosis." (PMID 36765354, 2023). "In some studies, increased plasma GDF-15 concentrationsover time have already provided strong evidence for poorer prognosis in patientswith CAD or heart failure." (PMID 39077481, 2023). "These dysregulated genes included heart failure biomarkers such as Nppa, Nppb, and Gdf15, which are wildly used in clinical diagnoses of heart failure." (PMID 36674797, 2023). "GDF-15 has been indicated in various biological functions, including inflammation, metabolism, cancer cachexia, solid tumor, renal and heart failure, atherosclerosis, and lung fibrosis." (PMID 35784345, 2022). "Increased expression of GDF-15 has a cardioprotective function, which has been observed in heart failure, atherosclerosis, and endothelial dysfunction." (PMID 35626917, 2022). "A systematic review study that included 21 clinical studies illustrated that GDF15 serum level was regarded as a novel biomarker of heart failure." (PMID 36140453, 2022). "GDF-15 also promotes cardiac fibrosis in heart failure and increases collagen turnover in MI as well as collagen deposition in atherosclerotic plaques." (PMID 35600479, 2022). "Another study showed that higher circulating GDF-15 levels were correlated to greater mortality in CKD patients and was also associated with a higher risk of heart failure." (PMID 35204349, 2022). "(2017) assessed the levels of GDF15 in 14,577 patients with stable coronary heart disease and showed that the levels of GDF15 to be correlated with heart failure death, cardiovascular death, cancer death, sudden death, and hospitalization for heart failure." (PMID 35068064, 2022). "Apart from that, upregulated levels of GDF-15 have been predominately studied in relation to major adverse cardiac incidents such as myocardial infarction or heart failure." (PMID 36034829, 2022).
heart failure (continued). "GDF15 is correlated with cardiovascular diseases such as atrial fibrillation, heart failure, and coronary artery disease." (PMID 35068064, 2022). "Several studies have shown that an increase in GDF-15 correlates with worsening clinical conditions in patients with heart failure or Fontan circulation, but studies report usual values above the 99th percentile upper reference limit (URL)." (PMID 35735800, 2022). "Elevated levels of GDF-15 have been demonstrated to be an independent predictor of heart failure related rehospitalization as well as death in patients with both diastolic and systolic heart failure after adjusting for troponin and BNP levels." (PMID 35390066, 2022). "GDF-15 is promising as a prognostic factor in patients with heart failure with preserved ejection fraction." (PMID 35626917, 2022). "In humans, circulating GDF15 is increased in cancer, heart failure, obesity, and also during physiological conditions such as exercise and pregnancy." (PMID 36545337, 2022). "GDF15 is reminiscent of a robust prognostic biomarker in the high-risk patients with CVD, including fatal arrhythmia, myocardial infarction and heart failure." (PMID 33670413, 2021). "In previous cohorts, patients with chronic kidney disease, heart failure, and cancer also showed an inverse correlation between serum GDF-15 levels and body mass index (BMI)." (PMID 34150865, 2021). "The use of established and emerging biomarkers, such as CRP and GDF-15, has shown significant promise as predictors of outcome in myocardial infarction and heart failure." (PMID 34221186, 2021). "Several clinical studies have found that higher levels of GDF-15 are associated with poor prognosis, including CVD, heart failure, and death in patients with CKD." (PMID 34992536, 2021). "At present, many studies have reported that GDF15 is upregulated in many disease processes such as heart failure, myocardial infarction, pulmonary embolism, liver injury, and so on." (PMID 34566964, 2021). "GDF-15 has recently been reported not to change with heart rate, in spite of its potential relevance in connecting heart failure outcomes and mechanisms through GDF-15 quantification." (PMID 34441356, 2021). "High GDF-15 concentrations were noted in hypertrophic and dilated cardiomyopathies, after volume overload, ischaemia and heart failure." (PMID 35053194, 2021). "Many recent clinical studies have confirmed the predictive value of GDF-15 for mortality and clinical courses in various diseases, such as cardiovascular disease, heart failure, and kidney diseases." (PMID 34441955, 2021). "GDF-15 is a stress-responsive cytokine and increases in various pathologic conditions such as heart failure, chronic kidney disease, diabetes, chronic obstructive pulmonary disease, and solid cancers." (PMID 34441955, 2021). "This produced circulating concentrations of human GDF15 similar to that reported in patients with cancer and heart failure." (PMID 34187898, 2021). "Though GDF-15 is not a cardiac-specific protein and elevated in many other tissues, namely liver, kidney, and lung, increased levels of GDF-15 have been observed in the setting of myocardial infarction, heart failure and cardiomyopathy." (PMID 33312062, 2020). "Elevated levels of GDF-15 have been reported in heart failure patients with an impact on mortality rates in heart failure with reduced and preserved ejection fraction." (PMID 33344515, 2020). "The magnitude of elevation in heart failure varies according to severity, comorbidities, and clinical setting but GDF15 levels in the normal range (<1200 pg/ml) are uncommon." (PMID 32310257, 2020). "With regards to levels of GDF-15, a significant elevation was present in all three types of heart failure compared to controls." (PMID 32326570, 2020). "In the cardiovascular field, GDF15 has been postulated to play a role in the pathophysiology of LV remodeling, hypertrophy and myocardial fibrosis, with substantial implications in heart failure." (PMID 32957481, 2020).
heart failure (continued). "In a contemporary clinical trial of pharmacotherapy in heart failure with reduced ejection fraction median, GDF15 levels were just over 1600 pg/ml, with an approximate 10% change in GDF15 levels observed per increase in NYHA class." (PMID 32310257, 2020). "In a mouse, postmyocardial infarction model of heart failure, Gdf15 is upregulated almost 20-fold at the mRNA level in the myocardium versus noninjured hearts, but plasma levels are not significantly different." (PMID 32310257, 2020). "A direct correlation between LV mass and GDF15 levels in a context of hypertrophy linked to AVS, heart failure or arterial hypertension had already been reported, also accounting for the increasing fibrosis grade observed with aortic valve disease progression." (PMID 32957481, 2020). "GDF-15 induces atrophy of C2C12 myotubes and is associated with acute muscle atrophy in heart failure and cachexia." (PMID 32927586, 2020). "Another study recruited 1142 patients with NSTEMI or STEMI were follow-up for 1.4 years, the result indicated that GDF-15 is a new marker for predicting death and heart failure in post-AMI patients." (PMID 32746821, 2020). "This was verified by numerous investigations demonstrating that high circulating levels of GDF-15 were related to the increased risks of heart failure, stroke, coronary heart disease, and cardiovascular mortality." (PMID 33239667, 2020). "Increased levels of GDF-15 are seen in patients with lower ejection fraction, diastolic dysfunction, and more severe symptoms of heart failure." (PMID 33419237, 2020). "Subsequently, GDF-15 was extensively investigated in relation to the development of heart failure, coronary heart disease, atrial fibrillation, and MI." (PMID 31772623, 2019). "Two studies were conducted on meta‐analysis of the relationship between GDF‐15 and the different prognosis of acute coronary syndromes and heart failure separately." (PMID 30697778, 2019). "In a recent meta-analysis on the prognostic power of GDF-15 in patients with heart failure, circulating GDF-15 levels were a strong prognosticator of all-cause mortality in heart failure patients." (PMID 29180833, 2017). "Secondly, GDF-15 is increased in experimental conditions of ischemia/reperfusion injury as well as in clinical settings of organ dysfunction like heart failure, myocardial infarction, and pulmonary embolism." (PMID 29180833, 2017). "BNP is well established and widely used clinically for diagnosis of heart disease especially heart failure; GDF15 was also recently proposed as an independent plasma biomarker for heart diseases." (PMID 28572090, 2017). "GDF-15 is also strongly induced in other cardiovascular conditions, such as heart failure, Takotsubo cardiomyopathy, and atherosclerosis." (PMID 27154403, 2016). "Although GDF15 has been reported to represent a biomarker for heart failure, elevated levels have also been found in the cell systems of liver, lung and kidney injury." (PMID 26537877, 2016). "At enrollment, 12 of 55 patients were in NYHA functional class III or IV heart failure and showed a significantly higher GDF-15 levels (2032.0 ± 1108.0 vs 1305.0 ± 619.0 ng/l, P = 0.002) as compared to those patients in NYHA functional class I and II." (PMID 27311391, 2016). "Recently, one study observed that GDF-15 is a novel promising biomarker in heart failure with normal ejection fraction (HFnEF)." (PMID 26273671, 2015). "In a recent study, the circulating concentration of GDF-15 was measured at baseline (n = 1734) and at 12 months (n = 1517) in patients randomised in the Valsartan Heart Failure Trial (Val-HeFT)." (PMID 24839357, 2014). "GDF15 is a newly recognized marker of heart failure, and our data implicate an additional role of DCMi for increased GDF15 expression." (PMID 18194512, 2008).
heart failure (continued). "Of note, GDF-15 upregulation has been demonstrated after various cardiovascular events triggering inflammation, endothelial activation and oxidative stress, including pressure overload, heart failure (HF), atrial fibrillation and atherosclerosis." (PMID 41590509, 2026). "Importantly, both sST2 and GDF-15 have been shown to significantly improve prognostic assessment in heart failure patients, but they provide complementary information over different time frames." (PMID 41590509, 2026). "Heart failure was associated with FGF23, IGFB-7, GDF-15, IL-6, and MyBPC3." (PMID 40496590, 2025). "Growth differentiation factor-15 (GDF-15) is a stress-responsive cytokine elevated in conditions associated with inflammation and oxidative stress, as well as in different types of cardiovascular events like heart failure and atrial fibrillation." (PMID 40564142, 2025). "Notably, drugs targeting GDF15 are currently being evaluated for the treatment of heart failure (NCT05492500)." (PMID 40765025, 2025). "In heart failure, GDF-15 is considered a robust prognostic marker." (PMID 41157213, 2025). "Growth differentiation factor (GDF)-15, a stress-responsive member of the transforming growth factor-β cytokine superfamily, is an independent determinant of prognosis in healthy subjects and patients with heart failure." (PMID 40385809, 2025). "However, the data from this work add to data on the important prognostic role of GDF-15 in patients with heart failure." (PMID 40141732, 2025). "According to the 2022 meta-analysis performed using data pooled from eight trials including 53,486 patients, GDF-15 consistently added prognostic information for cardiovascular death and hospitalization for heart failure across the spectrum of atherosclerotic cardiovascular disease." (PMID 39860501, 2025). "A complex model, including both NT-proBNP and GDF-15, may play a supplemental role to support the treatment based only on BNP and better predict all-cause mortality and heart failure rehospitalization." (PMID 40385809, 2025). "Unexpectedly, blocking GDF15 activity also attenuated the development of severe heart failure." (PMID 39312445, 2024). "•GDF-15 can provide clinicians with reliable prediction and disease assessment of heart failure." (PMID 38352663, 2024). "Similarly, GDF-15 serves as a biomarker in heart failure, a common complication in patients with coronary heart disease and in atrial fibrillation." (PMID 39000420, 2024). "Additionally, a current application for monoclonal anti-GDF-15 is in the treatment of heart failure, with Ponsegromab undergoing recruitment in a Phase II study." (PMID 39000420, 2024). "For instance, GDF-15 is upregulated in patients with coronary artery disease (CAD) compared to non-CAD controls, yielding a diagnostic value with an AUC of 0.9 for CAD; moreover, GDF-15 is greater in heart failure patients with ischemic heart disease than in controls without ischemic heart disease." (PMID 38828460, 2024). "The preoperative level of GDF15 serves as an independent marker of postoperative mortality and morbidity in cardiac surgery patients and those with heart failure, as it may reflect both severe cardiac disfunction and circulatory stress." (PMID 39766300, 2024). "Our findings warrant further studies to investigate the role of GDF15 in human heart failure." (PMID 39312445, 2024). "Several studies have shown that elevated levels of GDF-15 are associated with all-cause mortality in patients with heart failure caused by acquired heart disease, independent of known prognostic variables." (PMID 39711764, 2024). "We also show the relevance of GDF15 to lean mass and protein intake in patients with heart failure." (PMID 39312445, 2024). "Rising GDF-15 levels might indicate worsening myocardial stress and dysfunction, prompting adjustments in pacing strategies or the initiation of heart failure therapies." (PMID 39768671, 2024).
heart failure (continued). "Taken together, elevated GDF-15 levels after MI may exert a protective function by reducing immune cell recruitment and, thereby, MI complications, such as cardiac remodeling and heart failure." (PMID 39000420, 2024). "In a sub study of TOPCAT (Treatment of Preserved Cardiac Function Heart Failure with an Aldosterone Antagonist Trial), GDF-15 was labeled as an “intermediary metabolism” protein clustering with proteins associated with mineral metabolism including fibroblast growth factor-23 and osteoprotegerin." (PMID 36844723, 2023). "Furthermore, GDF-15 is reportedly strongly correlated with multiple cardiovascular diseases, such as heart failure and atherosclerosis." (PMID 38254638, 2023). "In addition, it is reported that GDF-15 is an effective marker of adverse events such as acute coronary syndrome, heart failure, and acute pulmonary embolism." (PMID 37288264, 2023). "Moreover, higher levels of GDF-15 have been shown to correlate with heart failure and with increased mortality in CKD; in fact, GDF-15 has been proposed as a helpful tool for the diagnosis of heart failure in dialysis patients." (PMID 37189644, 2023). "In this study, we aimed to determine whether YB-1 is modified in cardiac patients who develop heart failure, and we investigated YB-1’s influence on PE- and GDF15-induced hypertrophy as a predictor of the development of heart failure." (PMID 38203580, 2023). "Inthis study, GDF-15 was independently associated with fatal and nonfatal CVevents, and hospitalization for heart failure in stable CAD during nearly 9 yearsof follow-up." (PMID 39077481, 2023). "Given that GDF-15 level is increased in not only patients with vascular inflammation, coronary artery disease, and heart failure, it has been unclear if the totality of evidence in the literature concur that patients with type 2 diabetes were similarly affected." (PMID 35883490, 2022). "Moreover, the GDF15 has been reported to increase in various cardiometabolic and inflammatory disorders including heart failure and rheumatoid arthritis." (PMID 36140453, 2022). "In the presence of an ACS, a single measurement of GDF-15 and concentrations greater than 1800 ng/L were linked to an elevated risk of all-cause mortality, MACEs and hospitalization for heart failure, but not subsequent readmission for MI." (PMID 36012430, 2022). "Notably, sST2 and NT-proBNP were positively related to the plasma concentration of GDF-15, an innovative biomarker of heart failure which we previously assessed in a subgroup of patients." (PMID 36088327, 2022). "Third, wherever GDF-15/Albumin ratio is associated with cardiovascular disease or heart failure is not fully studied." (PMID 35204349, 2022). "GDF-15 has been described as a potent marker of cardiovascular events (death, recurrent heart failure, recurrent myocardial infarction) in various populations, including patients with myocardial infarction or heart failure." (PMID 34063283, 2021). "A release of TiNPs and, consequently, an uncontrolled increase in GDF-15 could in long term promote cardiac fibrosis and further exacerbate heart failure." (PMID 34975851, 2021). "Both IGFBP7 and GDF15 independently predict mortality and hospitalization for heart failure." (PMID 34217226, 2021). "Conditions where increased circulating GDF15 have been reported include but are not limited to pregnancy, exercise, aging, renal failure, cardiac failure, chronic inflammatory disease, neoplasia, and mitochondrial diseases as well as cytotoxic chemotherapy and ionizing radiation." (PMID 31853550, 2020). "GDF15 expression is increased in the myocardium of animal models of heart failure." (PMID 32310257, 2020). "The role of GDF15 in the pathogenesis of heart failure is poorly understood." (PMID 32310257, 2020). "Also novel blood biomarkers such as growth differentiation factor-15 (GDF-15) and galectin-3 have been linked to the pathophysiology and progression of heart failure." (PMID 32715081, 2020).